ENSG00000286856 (novel transcript, antisense to SLC2A2)
Gene: Long non-coding RNA gene on chromosome 3 (170,908,829 to 171,115,194, forward strand). Ensembl gene ENSG00000286856.
Gene Ontology:
Molecular function: pre-mRNA 5'-splice site binding
Biological process: mRNA 5'-splice site recognition
Cellular component: U1 snRNP